GHRL (ghrelin and obestatin prepropeptide)
Description:
Precursor of the appetite-regulating peptide ghrelin, including ghrelin-27 and ghrelin-28. [Ghrelin-27]: Ghrelin is the ligand for growth hormone secretagogue receptor type 1 (GHSR). Induces the release of growth hormone from the pituitary. Has an appetite-stimulating effect, induces adiposity and stimulates gastric acid secretion. Involved in growth regulation. [Ghrelin-28]: Ghrelin is the ligand for growth hormone secretagogue receptor type 1 (GHSR). Octanoylated ghrelin-28 is the most commonly found ghrelin and octanoylation is essential for the activation of the growth hormone secretagogue receptor type 1 (GHSR). Induces the release of growth hormone from the pituitary. Has an appetite-stimulating effect, induces adiposity and stimulates gastric acid secretion. Involved in growth regulation. [Obestatin]: May be the ligand for GPR39. May have an appetite-reducing effect resulting in decreased food intake. May reduce gastric emptying activity and jejunal motility (By similarity).
Synonyms: Ghrelin; MTLRP; obestatin
Tractability: Small molecule: a structure with a bound ligand is known; it belongs to a druggable protein family. Antibody: its Gene Ontology location is reachable by antibodies, with high confidence; UniProt places it where antibodies can reach, with medium confidence; UniProt predicts a signal peptide or a membrane-spanning region.
Target class: Secreted protein
Gene: Protein-coding gene on chromosome 3 (10,285,666 to 10,292,959, reverse strand). Ensembl gene ENSG00000157017.
Subcellular location: Secreted
Pathways (Reactome):
Signal Transduction: G alpha (q) signalling events; Peptide ligand-binding receptors
Metabolism of proteins: Synthesis, secretion, and deacylation of Ghrelin
Gene Ontology:
Molecular function: growth hormone-releasing hormone activity; protein binding; protein tyrosine kinase activator activity; ghrelin receptor binding; hormone activity
Biological process: actin polymerization or depolymerization; decidualization; dendrite development; negative regulation of apoptotic process; negative regulation of circadian sleep/wake cycle, REM sleep; negative regulation of endothelial cell proliferation; negative regulation of inflammatory response; negative regulation of interleukin-1 beta production; negative regulation of interleukin-6 production; negative regulation of tumor necrosis factor production; positive regulation of appetite; positive regulation of circadian sleep/wake cycle, non-REM sleep; positive regulation of corticotropin secretion; positive regulation of cortisol secretion; positive regulation of growth hormone secretion; positive regulation of MAPK cascade; positive regulation of synapse assembly; regulation of cell population proliferation; response to estrogen; response to hormone; adult feeding behavior; cartilage development; cortisol secretion; G protein-coupled receptor signaling pathway; gastric acid secretion; and 30 more
Cellular component: axon; extracellular region; endoplasmic reticulum lumen; secretory granule lumen; cytoplasm; glutamatergic synapse; neuronal dense core vesicle lumen; postsynapse; Schaffer collateral - CA1 synapse
Genetic constraint (gnomAD): Loss-of-function variants: 10 observed, 8.5 expected, observed/expected ratio (o/e) 1.18, 90% interval 0.72 to 1.82. That is too few expected variants to judge how well the gene tolerates losing a copy. Missense variants: 128 observed, 89.38 expected, observed/expected ratio (o/e) 1.43, 90% interval 1.24 to 1.66. Synonymous variants: 49 observed, 37.82 expected, observed/expected ratio (o/e) 1.3, 90% interval 1.03 to 1.64.
Homologues: Orthologues: chimpanzee GHRL (98% identical), macaque GHRL (95% identical), mouse Ghrl (84% identical), rat Ghrl (83% identical), pig GHRL (79% identical), dog GHRL (78% identical), guinea pig GHRL (67% identical).
Diseases named in the same sentence as GHRL in open-access papers:
GHRL is named in the same sentence as 72 diseases in open-access papers, as found by Europe PMC text mining. Sharing a sentence is not in itself a finding about the gene and the disease. The quoted sentences say what the papers report.
Obesity (26 papers, 2008 to 2025). Accumulation of substantial excess body fat. "The rs696217 (G > T) polymorphism in the GHRL gene has been associated in numerous studies with specific dietary patterns, higher fat intake, binge eating behavior, obesity, and larger waist circumferences." (PMID 39203789, 2024). "Many studies have been associated GHRL rs696217 T allele with BMI-related obesity, metabolic syndrome, binge eating, our results being aligned with the results in the literature." (PMID 39203789, 2024). "Specifically, CLOCK/CC, FTO/AA, and LEP/AA genotypes were strongly associated with higher obesity metrics and emotional eating scores, while GHRL/TT and MC4R/CC were linked to increased BMI and WHR." (PMID 39203789, 2024). "The G/G genotype of the A-604G SNP (single-nucleotide polymorphism) of the GHRL gene was found to be associated with altered serum ghrelin levels and obesity." (PMID 37764744, 2023). "GHRL located in the common segmental duplication of four patients, was known to be associated with obesity." (PMID 27099631, 2016). "Several studies have investigated the association between the GHRL rs26311, rs27647, rs696217, and rs34911341 polymorphisms with the risk of various diseases such as obesity, metabolic syndrome, type 2 diabetes, breast cancer, and colorectal cancer." (PMID 26599409, 2015). "A number of studies have shown associations between GHRL SNPs and obesity or related traits, although the results are contradictory." (PMID 20700400, 2010). "The Met72 allele of GHRL has been associated with earlier age at onset of obesity and higher BMI, but negative findings have also been reported." (PMID 20700400, 2010). "The GHRL gene, implicated in hunger signaling and regulation of energy balance, shows significant genotype-phenotype associations in our dataset where the TT genotype is associated with higher obesity metrics and emotional eating scores." (PMID 39203789, 2024). "Several studies have reported that GHRL polymorphisms might be associated with obesity, metabolic syndrome, type 2 diabetes, breast cancer, and colorectal cancer." (PMID 26599409, 2015). "Interestingly, both the rs696217 (Leu72Met) and rs4684677 (Gln90Leu) GHRL SNPs have been linked with obesity." (PMID 25376984, 2014). "Besides GHRL, the set of causal genes shared by obesity and cachexia comprised ADRB2, MC4R, and CNTF." (PMID 20815942, 2010). "Accordingly, GhRL expression changes induced by obesity are not limited to the gastrointestinal system organs but involve all the tissues of the organism." (PMID 39852916, 2025). "Three genes encode important components related to energy intake and energy expenditure balance such as Leptin (LEP), ghrelin (GHRL), melanocortin-4-receptor (MC4R), and the fat mass and obesity-associated gene (FTO)." (PMID 38863583, 2024). "Therefore, obesity might be associated with GHRL Leu72Met variant in our patient." (PMID 39036055, 2024). "The network of cardiometabolic proteins in obesity showed that the strongly higher-expressed LEP in the obese group interacts with the less-expressed GHRL and more-expressed GH1." (PMID 38732002, 2024). "Another configuration of a disposable immunosensing platform for the simultaneous determination of two obesity-related hormones, ghrelin (GHRL) and peptide YY (PYY) was also reported by this group." (PMID 29495294, 2018). "It is noteworthy that the role of ghrelin (GHRL) in periodontal health and disease has become the focus of a few recent studies due to its link to obesity as well as its modulatory functions on the immune system." (PMID 29317796, 2017). "Genes previously-reported to be associated with obesity and that reside within marker intervals at our peak LOD scores include GHRL, PPARG, HTR2A and ESR2." (PMID 21062459, 2010). "Besides meal-related fluctuations, GhRL levels decrease in obesity and increase in lean individuals, suggesting a role in long-term energy homeostasis." (PMID 39852916, 2025).
Obesity (continued). "Similarly, GHRL rs696217 has been tied to obesity and HDL cholesterol levels." (PMID 39858569, 2024). "On the other hand, WES analysis revealed a CNV involving exon 1 and exon 6–8 in TCF12 associated with HH and/or craniosynostosis, and a heterozygous missense variant, c.214C>A (p.Leu72Met) rs696217, in GHRL gene (NM_016362) associated with susceptibility to obesity (not shown)." (PMID 39036055, 2024). "Interestingly, other variants also known to influence reward/addiction associated processes or eating related behaviour such as OPRD1, BDNF, GHRL and CNR1, also revealed evidence of being associated with overweight/obesity or development to an adverse metabolic status." (PMID 26445370, 2015). "We calculated the Hardy-Weinberg Equilibrium (HWE) for six genes (CLOCK, GHRL, FTO, LEP, LEPR, MC4R) related to obesity, using genotype frequencies from our dataset." (PMID 39203789, 2024). "This study investigates the relationship between six obesity-related genes (CLOCK, FTO, GHRL, LEP, LEPR, MC4R) and their impact on BMI, WC, HC, WHR, and emotional eating behavior in 220 Romanian adults." (PMID 39203789, 2024). "Regarding CLOCK/CT, FTO/AT, GHRL/GT, LEP/GA, LEPR/AG, MC4R/CT we found intermediates values for weight, BMI, waist circumference, and WHR, reflecting moderate levels of body fat and obesity." (PMID 39203789, 2024). "Notably, individuals with the CLOCK (CC), FTO (AA), and LEP (AA) genotypes exhibited the highest BMI and WHR, while those with GHRL (TT), MC4R (CC), and LEPR (GG) genotypes, although showing lower values, were still correlated with overweight and obesity." (PMID 39203789, 2024). "However, circulating GHRL levels were decreased in obese individuals, and serum GHRL levels were inversely correlated with BMI, suggesting that GHRL is not directly involved in most cases of obesity." (PMID 22369141, 2012). "In enteroids from patients with obesity, 58 ± 12% of GHRL+ cells co-localized with MLN+ cells, while no co-localization was found between GHRL+ and GLP-1+ cells." (PMID 38125020, 2023).
diabetes (7 papers, 2018 to 2025). "In contrast to our study, the Finnish Diabetes Prevention Study found that GHRL rs696217 modified the effect of moderate-to-vigorous PA on weight and WC in their overweight cohort." (PMID 29755414, 2018).
breast carcinoma (6 papers, 2008 to 2023). "In a nested case-control study (648 cases/659 controls), none of the tagging single-nucleotide polymorphisms (SNP) in the GHRL gene were associated with the risk of breast cancer development." (PMID 31681567, 2019). "Increased risk in the GHRL SNP rs4684677 (OR 1.97-1.98, p = 0.08) associated with breast and esophageal cancers was exacerbated when confined to breast cancer (OR 2.38-2.40, p = 0.06)." (PMID 25376984, 2014). "Finally, associations of Gly57Gly SNP of GHSR with increased risk, and association of some rare haplotypes of GHRL with reduced risk of breast cancer were reported." (PMID 31681567, 2019). "Polymorphism of GHRL gene was linked to both all-cause and breast cancer-specific mortalities." (PMID 31681567, 2019). "This study suggests that the rs696217 and rs2075356 ghrelin gene (GHRL) polymorphisms may protect carriers against breast cancer, and the rs4684677 GHRL and rs572169 GHSR polymorphisms may increase the risk among carriers." (PMID 25376984, 2014). "Abnormally high expression of GHRL is not only observed in gastrointestinal tumors but also in other types of cancer including breast cancer, renal cell carcinoma, and ovarian cancer." (PMID 36241983, 2022). "In contrast, the rs4684677 GHRL and the rs572169 GHSR polymorphisms conferred increased breast cancer risk (OR 1.97-1.98, p = 0.08 and OR 1.42-1.43, p = 0.08, respectively)." (PMID 25376984, 2014). "The GHRL rs2075356 (3056 T > C) and GHSR rs572169 (Gly57Gly) SNPs were found to be associated with 20% increased risk of breast cancer in a European study with 1,324 cases and 2,360 controls." (PMID 25376984, 2014). "However, another nested case-control (1,359 cases/2,389 controls) reported associations of some polymorphisms (GHRL rs171407-G allele and GHSR 2948694-GG genotype) with increased risk of breast cancer." (PMID 31681567, 2019). "Increased risks were also observed in the co-dominant model of breast cancer studies for the rs4684677 GHRL SNP (OR 1.11, p = 0.23) and the GHSR rs572169 SNP, both overall and in breast cancer (OR 1.08-1.10), with borderline significance (p = 0.05), all homogeneously obtained (I2 = 0-46%)." (PMID 25376984, 2014). "A meta-analysis of case–control studies showed that the rs4684677 polymorphism in the GHRL gene and the rs572169 polymorphism in the GHSR gene confer an increased risk of breast cancer, whereas the rs696217 and rs2075356 polymorphisms in the GHRL gene protect carriers against breast cancer." (PMID 38137497, 2023). "Similarly, a non-significant decrease in the risk of the GHRL polymorphism, rs2075356, in breast and colorectal cancer (OR 0.78, p = 0.43-0.45) was unaltered when confined to breast cancer studies (OR 0.78, p = 0.43-0.45)." (PMID 25376984, 2014). "Non-significant, decreased risks associated with the rs696217 (OR 0.61-0.63, p = 0.09-0.11) GHRL polymorphism in breast, colorectal, esophageal and colorectal cancer were not altered when analyses were confined to breast cancer studies alone (OR 0.82-0.83, p = 0.57-0.60)." (PMID 25376984, 2014). "In summary, our results indicate that GHRL and GHSR SNPs may be involved in the pathophysiology of breast cancer." (PMID 25376984, 2014).
metabolic syndrome (6 papers, 2012 to 2024). A cluster of metabolic risk factors for CARDIOVASCULAR DISEASES and TYPE 2 DIABETES MELLITUS. "Our research group has already observed in a previous work that an infant with VACTERL and esophageal atresia carried a missense mutation on GHRL linked to metabolic syndrome." (PMID 34715892, 2021). "Another is the ghrelin (GHRL) rs696217 in which amino acid substitution from leucine to methionine may increase susceptibility to obesity and metabolic syndrome." (PMID 29755414, 2018). "Specific SNPs of GHRL have been associated with variations in BMI, blood pressure, high-density lipoproteins, low-density lipoproteins, serum cholesterol, blood glucose, and metabolic syndrome." (PMID 22369141, 2012).
colorectal cancer (4 papers, 2010 to 2019). A primary or metastatic malignant neoplasm that affects the colon or rectum. "Associations of GHRL polymorphisms with colorectal cancer risk in the German cases and controls." (PMID 20920174, 2010). "GHRL rs27647-T and rs35683-C alleles were associated with decreased risk of colorectal cancer in Czech Republic (680 cases/593 controls), but not German (569 cases/726 controls), population." (PMID 31681567, 2019).
gastric cancer (4 papers, 2021 to 2024). A primary or metastatic malignant neoplasm involving the stomach. "Overall, AIDPS plays a critical role in gastric cancer prognosis, genomic variations, immune cell infiltration and immunotherapy response, and targeting GHRL expression holds promise for personalized treatment." (PMID 38752750, 2024). "Correlation of GHRL mRNA expression and clinical prognosis in gastric cancer with different clinicopathological factors by Kaplan–Meier plotter." (PMID 37469414, 2023). "Conversely, the expression of genes encoding for Ghrelin (GHRL) and Kallikrein Related Peptidase 11 (KLK11) was decreased in intestinal gastric cancer compared with diffuse histotype." (PMID 34012923, 2021). "However, the correlation of GHRL to prognosis and tumor-infiltrating lymphocytes in gastric cancer (GC) remains unclear." (PMID 37469414, 2023). "For these reasons, our results suggest that FPR2, CARD14, CXCR2, EFNA2, CXCR1, AQP9 TRIP13, along with GHRL and KLK11, could be used as promising biomarkers for gastric cancer diagnosis or prognostic evaluation." (PMID 34012923, 2021).
acute pancreatitis (2 papers, 2017). An acute inflammatory process that leads to necrosis of the pancreatic parenchyma. "GHRL induced anti-inflammatory cytokine IL-4, which suppressed IL-1β expression in cerulein-induced acute pancreatitis." (PMID 29068376, 2017). "Obestatin, 23-amino-acid-peptide, colocalized with GHRL in human pancreas, decreased serum level of proinflammatory IL-1β and improved pancreatic blood flow in rats with cerulein-induced acute pancreatitis as well as ischemia/reperfusion-induced acute pancreatitis of rats." (PMID 29068376, 2017).
alcohol use disorder (2 papers, 2011 to 2013). "In human genetic studies a GHRL haplotype has been associated with paternal heredity of alcohol-use disorder, of increased weight in alcohol dependent individuals, as well as with increased sucrose consumption, as shown in the present study." (PMID 21448464, 2011). "Additionally, associations between a GHRL haplotype and paternal heredity of alcohol use disorder in females as well as increased weight in alcohol dependent males has been reported." (PMID 23579732, 2013).
Anorexia (2 papers, 2019 to 2025). Lack of desire to eat (loss of appetite). "Pharmacological studies demonstrated that EA treatment at CV12 reduces the levels of plasma monoamine neurotransmitters 5-HT, 5-HIAA, DA, and NE; while simultaneously stimulating the expression of GHRL and NPY to alleviate cisplatin-induced anorexia in rats." (PMID 31635295, 2019).
chronic hepatitis C (2 papers, 2015 to 2020). "A study on the influence of polymorphism in Ghr gene (GHRL) on hepatic fibrosis in patients with chronic hepatitis C, found that certain mutations in GHRL were associated with more severe liver fibrosis compared to wild type GHRL23." (PMID 32994489, 2020). "One study assessing 284 Spanish patients with chronic hepatitis C suggested that GHRL rs26312 and rs27647 polymorphisms influenced the progression of liver fibrosis in patients with this illness." (PMID 26599409, 2015).